EZH2 (enhancer of zeste 2 polycomb repressive complex 2 subunit)
Diseases named in the same sentence as EZH2 in open-access papers (continued):
Sharing a sentence is not in itself a finding about the gene and the disease.
prostate carcinoma (continued). "And SChLAP1/EZH2 could also promote prostate cancer tumor development via the interaction of microRNA-DNMT3a signaling pathways in xenograft nude mice." (PMID 33589600, 2021). "SChLAP1 directly binds with EZH2 and repressed multiple miRNA expression on chromosome 5 including the miR-340-3p in prostate cancer cells through recruiting H3K27me3 to mediate promoter methylation modification of miR-340-5p/miR-143-3p/miR-145-5p to suppress gene transcription." (PMID 33589600, 2021). "Finally, the roles of SChLAP1/EZH2 and the downstream miRNA-DNMT3a loop in prostate cancer pathogenesis were further validated by cellular and animal tumorigenic models." (PMID 33589600, 2021). "Furthermore, EZH2-dependent H3K27me3 has an impact on the decreased expression of inhibitor of DNA-binding/differentiation protein 4 in prostate cancer." (PMID 34401209, 2021). "Moreover, EZH2 knockdown produced similar outcomes as GSK343 in prostate cancer cells, while EZH2 overexpression induced opposite alterations, which further validated the roles of EZH2 in regulating the miRNA expression." (PMID 33589600, 2021). "In melanoma, prostate cancer, hepatocellular cancer and colon cancer, EZH2-induced epigenetic marks inhibit Th1 polarization and IFN-γ-JAK-STAT signaling, with EZH2 knockdown or pharmacologic inhibition using DZNep or GSK126, restoring IFN-γ-induced gene expression." (PMID 34163486, 2021). "EZH2 can also co-regulate prostate cancer stem cell properties with BRCA1." (PMID 33985534, 2021). "Altogether, our results suggest that SChLAP1 enhanced the proliferation, migration, and tumorigenicity of prostate cancer cells through interacting with EZH2 to recruit H2K27me3 and mediate promoter methylation modification of miR-340-5p/miR-143-3p/miR-145-5p with a DNMT3a-feedback loop." (PMID 33589600, 2021). "We reasoned that these genes might closely mirror the degree of ERG/EZH2 activation in prostate cancers." (PMID 34230470, 2021). "Whether or how PHF19 modulates the function and targets of the EZH2 in prostate cancer remains to be explored." (PMID 32155117, 2020). "However, how the EMT process contributes to prostate cancer progression, especially in the context of EZH2 overexpression, remains elusive." (PMID 31636385, 2020). "Additionally, hsa-miR-141, a miRNA that has been reported to target EZH2 in prostate cancer, was included because of its significant correlation with EZH2 in ovarian cancer." (PMID 33718109, 2020). "In a study of 104 prostate cancer patients, high EZH2 expression was associated with lymph node involvement, seminal vesicle invasion, and moderately or poorly differentiated grade." (PMID 33050946, 2020). "However, further studies are needed to clarify the differences in thephysiological function and mechanisms of USP7 and USP44 as EZH2 protein stabilizersin prostate cancer." (PMID 32453339, 2020). "It is reported that lncRNA MALAT1 binds to EZH2 in castration-resistant prostate cancer." (PMID 31830649, 2020). "Thus, wetested the sensitivity of prostate cancer cells to EZH2 inhibitors incombination with the USP7-specific inhibitor P5091." (PMID 32453339, 2020). "Moreover, another research illustrated that USP7 elevates EZH2 stability by mediating EZH2 deubiquitination in prostate cancer cells." (PMID 33308321, 2020). "Furthermore,ectopic introduction of EZH2 restored the cell migration, invasion, andsphere-forming potential of prostate cancer cells, which had been decreased byUSP7-knockdown." (PMID 32453339, 2020). "Likewise, cytoplasmic EZH2 was also reported to be lowly expressed in benign prostate epithelial cells but highly expressed in prostate cancer." (PMID 33327550, 2020). "Beyond prostate cancer cell lines, we also observed a significant reverse correlation between EZH2 and HNF1B expression in patient samples, and the high EZH2 and low HNF1B pattern is strongly associated with poor prognoses and advanced metastatic state (our own collection and public database)." (PMID 31636385, 2020).
prostate carcinoma (continued). "Taken together, our findings established a previously unknown connection between HNF1B and EZH2 in prostate cancer samples and cell lines." (PMID 31636385, 2020). "Indeed, recent studies reported that EZH2 can negatively regulate miR-200c expression in renal cancer and prostate carcinoma via the epigenetic regulation." (PMID 33168810, 2020). "Interestingly, it has been shown that let-7 mediated control of Ezh2 gene expression in prostate cancer cells, as it recognized a specific motif at the Ezh2 3′-UTR." (PMID 33187138, 2020). "To identify the downstream target(s) of EZH2 involved in prostate cancer progression, we explored the public EZH2 and histone H3K27me3 ChIP-seq (chromatin immunoprecipitation assays with sequencing) datasets of various prostate cancer cell lines." (PMID 31636385, 2020). "We found that HNF1B could be epigenetically repressed by EZH2 in prostate cancer cell lines, and its expression is reversely correlated with EZH2 expression in several cohorts of prostate cancer samples, including TCGA database and in-house collection." (PMID 31636385, 2020). "It has been reported that EZH2 directly inhibits miR-29, miR-26, miR-101, and miR-30 families in B cell lymphomas, chronic lymphocytic leukemia, hepatocellular carcinoma, malignant peripheral nerve sheath tumor cells, and prostate cancer 33, 36, 52-54." (PMID 32754259, 2020). "Additionally, studies show that high expression of EZH2 is related to bad prognosis in prostate cancer, and it is also an indicator to distinguish indolent prostate cancer from prostate cancer with lethal evolution." (PMID 33299862, 2020). "USP44 can induce the genesis of prostate cancer cells partly by stabilizing EZH2." (PMID 32164618, 2020). "Therefore, further understanding of the regulatory network of EZH2 in prostate cancer is still urgently needed." (PMID 31636385, 2020). "Moreover, high expression of EZH2 in prostate cancer cells increases the level of histone H3K27me3 in the promoter region of the tumor suppressor gene ID4." (PMID 33256840, 2020). "Furthermore, MEG3 facilitates H3K27 trimethylation of EN2 through binding with EZH2, thus suppressing the development of prostate cancer." (PMID 33061817, 2020). "TCGA database analysis showed that SNHG1 and EZH2 were highly expressed in prostate cancer tissue." (PMID 33194612, 2020). "Importantly, we find that higher HNF1B expression strongly predicts better prognosis of prostate cancer, alone or together with lower EZH2 expression." (PMID 31636385, 2020). "In addition, DNMT1 has been shown to physically interact with EZH2 to provide site-specific differential methylation in prostate cancer." (PMID 30089854, 2019). "While effectively inducing loss of viability of PTEN-positive 22Rv1 prostate cancer cells, EZH2 inhibitor failed to inhibit growth of PTEN-negative C4-2 prostate cancer cells." (PMID 31410199, 2019). "Enhancer of zeste 2 (EZH2) promotes prostate cancer progression." (PMID 31104332, 2019). "We therefore sought to determine whether EZH2 ASO can act as EZH2 inhibitor to treat prostate cancer cells." (PMID 31410199, 2019). "Interestingly, a recent study showed that EZH2 inhibitors upregulated androgen receptor expression and sensitized the prostate cancers to anti-androgen therapy." (PMID 31704972, 2019). "ChIP-qPCR analysis further confirmed that there was substantial enrichment of EZH2 binding at the FOXO1 promoter in both C4-2 (PTEN-negative) and 22Rv1 (PTEN-positive) prostate cancer cells, indicating that EZH2 binds to the FOXO1 gene promoter in both cell lines." (PMID 31410199, 2019). "This might be a general mechanism for N-Myc to differentially regulate its target genes in androgen-dependent and -independent prostate cancer and EZH2 or other protein factor works together with N-Myc to make this switch." (PMID 30657058, 2019).
prostate carcinoma (continued). "Of note, EZH2 can act as a co-activator of other transcription factors upon phosphorylation of Serine21 in prostate cancer cells opening up the possibility that EZH2 could act as both a transcriptional repressor and co-activator in epileptogenesis." (PMID 31891591, 2019). "Additionally, FOXC2-AS1 facilitates the proliferation and progression of prostate cancer via targeting miR-1253/EZH2." (PMID 31801629, 2019). "Interestingly, EZH2 serves as a coactivator of AR through direct interaction to facilitate its oncogenic function in cells of castration-resistant prostate cancer." (PMID 31481081, 2019). "Besides, several miRNAs such as miR-182 and miR-101 can be included by hypoxia in prostate cancer, epigenetic modulators such as Enhancer of zeste homolog 2 (EZH2) can also be regulated by HIF-1α induction." (PMID 29699590, 2018). "RUNX1 was reported as a target of AR, and its promoter was bound by EZH2 in prostate cancer." (PMID 29921304, 2018). "This differs from what has been recently described in other prostate cancer models of lineage plasticity in which EZH2 inhibition resulted in re-expression of the AR26,28, possibly due to an earlier more “plastic” disease state in those models where AR was not completely absent prior to therapy." (PMID 29921838, 2018). "Moreover, EZH2 has coactivator functions of a transcription factor by polycomb-independent activity in castration-resistant prostate cancer cells." (PMID 29805743, 2018). "In addition, the oncogenic activity of EZH2 in castration-resistant prostate cancer cells is polycomb independent but dependent on EZH2 phosphorylation at Ser54." (PMID 29343685, 2018). "Previous study showed the expression of EZH2 could be regulated by HIF-1α/HIF-1β dependent hypoxic pathway in prostate cancer." (PMID 29699590, 2018). "EZH2 expression is correlated with Myc expression in prostate cancer." (PMID 29556394, 2018). "Recently, miR-31 was also identified to be repressed by EZH2 in prostate cancer." (PMID 29401683, 2018). "Therefore, we detected the EZH2 mRNA and protein expression of prostate cancer cells under normoxic or hypoxic conditions." (PMID 29699590, 2018). "Interestingly, TSP1 is among a list of potential EZH2-repressed targets in gene expression profiles of prostate cancer cells upon EZH2 modulation." (PMID 30287808, 2018). "Collectively, these data establish that TSP1 is an EZH2 repressed target in prostate cancer cells." (PMID 30287808, 2018). "EZH2 is so prominently involved in aggressive cell growth, metastasis, drug resistance and stem cell maintenance that it has become an attractive therapeutic target in prostate cancer." (PMID 28403887, 2017). "Both Snail and EZH2 may be influenced by ERK signalling, and ERK signaling has been further implicated in regulating prostate cancer stem cells." (PMID 28038472, 2017). "Also, PSP94, SLIT2 and CDKN2A are downstream targets of EZH2 in prostate cancer that mediates tumorigenesis and metastasis." (PMID 28410242, 2017). "EZH2, despite of its ability to trimethylate lysine 27 in histone H3, when phosphorylated, suppressed its methyltransferase activity, and switched to a coactivator for its oncogenic function in prostate cancer." (PMID 28390392, 2017). "Increased H3K27me3 marks could be explained by the activity of the PcG such as EZH2, which is frequently over-expressed in prostate cancer." (PMID 28403887, 2017). "Enhancement of EZH2 expression by c-MYC has been described in prostate cancer and AML." (PMID 26497210, 2016). "EZH2 was previously shown to repress E-cadherin in breast, pancreatic and prostate cancer cells." (PMID 27563817, 2016). "EZH2 has high prognostic value for prostate cancer and potentially contributes to the development of a subtype of genetically unstable and particularly aggressive prostate cancers." (PMID 27172794, 2016). "Interestingly, EZH2 demonstrates similar expression patterns in prostate cancer as HELLS with expression in a minority of tumor cells." (PMID 27191985, 2016).
prostate carcinoma (continued). "Moreover, in prostate cancer, EZH2 can repress the expression of tumor suppressors such as DAB2IP, p16 (CDKN2A), CDK4, E-cadherin (CDH1), MSMB, Ras (KRAS), NF-κB (NFKB1), EMT regulator." (PMID 27835578, 2016). "Furthermore, in breast and prostate cancer EZH2 downregulates the Raf-1 kinase inhibitor protein (RKIP) potentially leading to tumor progression and metastasis." (PMID 27125524, 2016). "Thus, the combination of a low dose TopIIa inhibitor with a EZH2 inhibitor is beneficial against aggressive prostate cancer." (PMID 27752293, 2016). "Importantly, in prostate cancer EZH2 is decreased by androgens, while androgen deprivation increases the expression of EZH2, which downregulates E-cadherin thereby promoting cell migration and cancer progression." (PMID 27793053, 2016). "Therefore it will be interesting to elucidate if silibinin-mediated alterations in gene expression in prostate carcinoma cells are due to decreased EZH2 abundance or altered EZH2 function." (PMID 28042859, 2016). "In addition, 82% (27/33) of SOX2+ prostate cancer cases were EZH2+ type, and 100% (33/33) of cases were CD44+." (PMID 27447616, 2016). "Similarly, it was found that inhibition of EZH2 with GSK126 induces apoptosis in multiple castrate resistant prostate cancer cell lines." (PMID 27793053, 2016). "SLIT2 is a representative target of EZH2 in prostate cancer and its promoter is occupied with EZH2." (PMID 25537508, 2015). "Moreover, EZH2 is important in maintaining the pluripotency of embryonic stem cells or prostate cancer stem cells." (PMID 25537508, 2015). "Based on data demonstrating epigenetic repression of miR-31 expression by DNA methylation and EZH2-mediated H3K27me3 epigenetic mark in melanoma, leukemia and prostate cancer, we examined the role of epigenetic regulation of miR-31 in invasive esophageal cancer." (PMID 25644061, 2015). "In prostate cancer cells, EZH2 overexpression is known to promote cancer progression." (PMID 25537508, 2015). "Genes up-regulated in PC3 cells (prostate cancer) after knockdown of EZH2 by RNAi." (PMID 26043758, 2015). "Recent evidence suggests that the prostate cancer (PCa)-specific up-regulation of certain genes such as AMACR, EZH2, PSGR, PSMA and TRPM8 could be associated with an aberrant expression of non-coding microRNAs (miRNA)." (PMID 24517338, 2014). "In addition, Genomatix MatInspector analysis showed that transcriptional repressor EZH2 and co-repressor CtBP1, both of which are overexpressed in prostate cancer, contain HIF1α binding sites at their promoters." (PMID 25115393, 2014). "EZH2 could impede epithelial differentiation and contribute to prostate cancer progression because it was shown to directly modulate the transcriptional output of AR." (PMID 25277175, 2014). "The EZH2-DNMT dependent mechanism at least in prostate cancer suggest that targeting this pathway through specific inhibitors resulting in general epigenetic re-programming including up-regulation of ID4 could be a strong therapeutic strategy." (PMID 25115397, 2014). "The promoter regions showing higher H3K27me3 marks in K562 and HUVEC cells were used to investigate whether these regions are also enriched for EZH2 and H3K27me3 in prostate cancer cells." (PMID 25115397, 2014). "Collective observations led us to hypothesize that increased EZH2 expression could be involved in down-regulation of ID4 in prostate cancer." (PMID 25115397, 2014). "It was also reported that DIM upregulated the expression of the let-7 family and reduced the expression of its target, histone-lysine N-methyltransferase (EZH2), to inhibit self-renewal and clonogenic capacity in LNCaP, C4-2B, and PC-3 prostate cancer cell lines." (PMID 25254214, 2014). "Additionally over-expression of AR and EZH2 appeared to be important to promote the progression of prostate cancer." (PMID 25535400, 2014). "Previous studies have identified EZH2 as upregulated in prostate cancer." (PMID 25535400, 2014).
prostate carcinoma (continued). "The data presented here supports an EZH2 dependent epigenetic silencing of ID4 in prostate cancer." (PMID 25115397, 2014). "Knockdown of EZH2 in prostate cancer cell lines results in decreased cellular growth and invasion." (PMID 25115397, 2014). "Whether the EZH2-DNMT mechanism is specific to prostate cancer or a more general pro-cancer pathway involved in ID4 gene silencing remains to be investigated." (PMID 25115397, 2014). "Increased EZH2 but decreased ID4 expression in prostate cancer strongly supports this model." (PMID 25115397, 2014). "Similarly, EZH2 suppressed the expression of miR-181a, miR-181b, miR-200b, miR-200c, let-7 and miR-203 in prostate cancer." (PMID 24261995, 2013). "Interestingly, recent evidence suggests that phosphorylation of EZH2 by AKT at S21 site leads to PRC2-independent association of EZH2 with androgen receptor and activation of its target genes in prostate cancer cells." (PMID 23494175, 2013). "For example, MYC can induce the accumulation of EZH2 in prostate cancer." (PMID 24261995, 2013). "Considering the role of EZH2 in PCSCs and the relationship between EZH2 and miR-101, introduction of miR-101 to silence EZH2 could be a potential therapeutic strategy for prostate cancer." (PMID 23739676, 2013). "A more recent study analyzing the function of EZH2 in breast and prostate cancer lines has reported that the recruitment of EZH2 and Suz12 (both PRC2 subunits) to the promoter region of the tumor-suppressor gene RKIP is accompanied by H3K27 and H3K9 trimethylation." (PMID 23826629, 2013). "Enhancer of zeste homolog 2 (EZH2), a key component of the polycomb repressor complex (PRC) 2 which mediates histone H3 methylation at lysine 27 (H3K27), has been linked to aggressive progression of breast and prostate cancers." (PMID 24977105, 2012). "With regard to its transcriptional regulation, a hypothetic role can be assigned to MYC, since recent gene expression profiling data revealed up-regulation of genes located on chromosome 8q, including MYC, in PDSS, and MYC has been reported to induce EZH2 in prostatic carcinoma." (PMID 23110793, 2012). "The invasive phenotype of RWPE-1 cells was induced by EZH2 overexpression as observed above, but it was significantly suppressed by cooverexpression of TIMP3, providing direct evidence that the repression of TIMP3 by EZH2 results in increased invasive activity of prostate cancer cells." (PMID 22272343, 2012). "To investigate whether high levels of EZH2 expression is correlated with the invasive phenotype of prostate cancer cells, we first determined protein levels of EZH2 in human prostate cell lines (LNCaP, PC3, and DU145)." (PMID 22272343, 2012). "Early studies showed that high levels of EZH2 expression are associated with invasion and metastasis of malignant tumors such as breast and prostate cancers and that EZH2 overexpression transforms the benign prostate cells RWPE-1 and BPH1 and the immortalized breast epithelial cells." (PMID 22272343, 2012). "We examined the expression of EZH2 in PCa cell lines and immortalized prostate epithelial cell lines, and found that EZH2 was expressed in prostate cancer cells at relatively higher levels compared to immortalized prostate epithelial cell lines: PZ-HPV-7 and RWPE-1 cells." (PMID 22442719, 2012). "The nature of this discrepancy is unclear but might arise from differences in expression levels of EZH2 in the prostate cancer cells tested." (PMID 22272343, 2012). "For example, it is quite plausible that Myc may stimulate prostate cancer initiation, in part via EZH2-mediated chromatin remodeling and gene silencing." (PMID 21941025, 2011). "The frequent and early overexpression of Myc in PIN and primary prostate cancer cases may account in part for the common upregulation of EZH2 in these lesions." (PMID 21941025, 2011). "Thus, in these Myc-driven murine models of prostate cancer, EZH2 elevation occurs downstream of Myc induction." (PMID 21941025, 2011).